ATXN2 (ataxin 2)
Diseases named in the same sentence as ATXN2 in open-access papers (continued):
Sharing a sentence is not in itself a finding about the gene and the disease.
lung carcinoma (2 papers, 2019 to 2023). "A study using sequencing analysis of exome and mRNA‐seq observed recurrent mutations of ATXN2 in nonsmokers patients with lung cancer, revealing the nonnegligible role of ATXN2 in the progress and prognosis of cancer patients." (PMID 37449541, 2023).
sarcoidosis (2 papers, 2022 to 2025). Sarcoidosis is a multisystemic disorder of unknown cause characterized by the formation of immune granulomas in involved organs. "Overall, SNPs from the following genes have already been identified in previous studies on sarcoidosis (GWAS or other): CCDC88B, ANXA11, IL23R, FAM117B, CCL24, ATXN2/SH2B3." (PMID 41466414, 2025). "Previous studies have connected the genetic variation in the SH2B3/ATXN2 region with CD4+ T cells counts, and a variety of autoimmune conditions, including alopecia areata and sarcoidosis." (PMID 35386719, 2022).
systemic lupus erythematosus (2 papers, 2023 to 2025). An autoimmune multi-organ disease typically associated with vasculopathy and autoantibody production. "For instance, we identified one genomic region (gene ATXN2) with a high posterior probability (PP4 = 0.98) between systemic lupus erythematosus and POAG." (PMID 37386247, 2023). "In our colocalization analysis, we further identified a shared genomics region near ATXN2 between systemic lupus erythematosus and POAG." (PMID 37386247, 2023).
Tetralogy of Fallot (2 papers, 2013 to 2017). A congenital cardiac malformation comprising pulmonary stenosis, overriding aorta, ventricular septum defect, and right ventricular hypertrophy. "Analysis using Gene Ontology /pathway, Online Mendelian Inheritance in Man, PubMed and other databases revealed that PEX5, NACA, ATXN2, CELA1, PCDHB4 and CTBP1 were associated with Tetralogy of Fallot." (PMID 29291004, 2017). "Our findings identify PEX5, NACA, ATXN2, CELA1, PCDHB4 and CTBP1 mutations as underlying genetic causes of isolated tetralogy of Fallot." (PMID 29291004, 2017). "The rs11065987 near the BRAP and ATXN2 gene was associated with both LDL and TC and has been reported to be a risk SNP of Tetralogy of Fallot." (PMID 27896059, 2013).
Allgrove syndrome (1 paper, 2021). "Therefore, we hypothesize that increased Ataxin-2 expression as identified by our unbiased proteomic profiling contributes to the pathophysiology of Allgrove syndrome." (PMID 33563298, 2021).
Atrophy (1 paper, 2017). Any weakening or degeneration, especially through lack of use. "In addition, we observed strong connectivity of ATXN2 and AR with HTT in the pons that has been described to undergo atrophy in SCA2." (PMID 29249939, 2017).
autistic spectrum disorders (1 paper, 2009). "Atxn2 has not only been implicated in human neurodegenerative disease, but it remains a candidate for autistic spectrum disorders and bipolar disorder due to its interaction with A2BP1/Fox-1." (PMID 19617910, 2009).
cerebellar degeneration (1 paper, 2015). Degeneration of the cerebellum. "As cerebellar degeneration is predominant in SCA2, we further examined the expression patterns of the ATXN2 transgene in discrete areas of the cerebellum using laser-capture microdissection (LCM)." (PMID 25902068, 2015).
colon tumors (1 paper, 2024). "In colon tumors, ATXN2 acts as a co-regulator of ZBRK1, enhancing its own transcription (SCA2 gene)." (PMID 39039334, 2024). "Significantly, ATXN2 is reduced in colon tumors with low ZBRK1 transcripts." (PMID 39039334, 2024).
corticobasal degeneration (1 paper, 2023). "Ataxin-2 intermediate-length polyglutamine expansion is associated with increased ALS risk, and C9ORF72 intermediate-length repeat expansion is associated with corticobasal degeneration and ALS." (PMID 36672065, 2023).
corticobasal syndrome (1 paper, 2023). Corticobasal syndrome (CBS) is a rare neurodegenerative disease characterized by multifaceted motor system dysfunctions and cognitive defects such as asymmetric rigidity, bradykinesia, limb apraxia, and visuospatial dysfunction. "Whereas SCA2 patients demonstrate only an uninterrupted CAG repeat within ATXN2, a patient with corticobasal syndrome was reported which demonstrated 27/39 CAG repeats within ATXN2 with a CAG repeat interrupted by three (intermediated allele) or four (expanded allele) CAA motifs." (PMID 36894829, 2023).
glioma (1 paper, 2025). A benign or malignant brain and spinal cord tumor that arises from glial cells (astrocytes, oligodendrocytes, ependymal cells). "ATXN2 knockdown was performed in glioma cell lines to assess its effects on proliferation, migration, and invasion." (PMID 40982134, 2025). "ATXN2 was highly expressed in GBM tissues, localized in neurons and glioma cells, and its knockdown enhanced proliferation, migration, and invasion via ERK phosphorylation." (PMID 40982134, 2025).
hepatocellular carcinoma (1 paper, 2019). A malignant tumor that arises from hepatocytes. "Our data showing that Ataxin-2 modulates ZIKV gene expression in the hepatocellular carcinoma cell line Huh7 is exciting, and additional studies in neuronal cells would illuminate the role of this protein in cellular dysfunction and neurodegeneration following intrauterine ZIKV infection." (PMID 30944179, 2019).
hyperthyroidism (1 paper, 2018). Overactivity of the thyroid gland resulting in overproduction of thyroid hormone and increased metabolic rate. "The identified variants are therefore expected to be a mix of variants, which have been previously associated with hypo or hyperthyroidism (e.g., TPO, FOXE1, and ATXN2) and variants that lead to a TSH level, which is slightly above or below the population-based reference ranges." (PMID 30367059, 2018).
Lewy body dementia (1 paper, 2025). A progressive form of dementia characterized by the presence of protein deposits called Lewy bodies in the midbrain and cerebral cortex, and loss of cholinergic and dopaminergic neurons. "We screened whole genome sequencing data from the AMP PD Lewy Body Dementia (LBD) and PD cohorts for 37 REs associated with neurological disorders, and identified both interrupted and uninterrupted REs in ATXN2 in 4/2431 PD and 2/2468 LBD cases, but none in controls." (PMID 41310328, 2025).
memory impairment (1 paper, 2023). "We selected the basal forebrain as the brain area for drug injection in this study to observe whether basal forebrain BDNF signaling activation by ASO targeting ATXN2 mRNA could reverse the memory impairments induced by sleep deprivation." (PMID 37072935, 2023). "In this study, we proposed and tested the hypothesis that ASOs targeting ATXN2 in the basal forebrain could increase BDNF expression, thereby modulating sleep deprivation‐induced memory impairments." (PMID 37072935, 2023).
osteoporosis (1 paper, 2024). A condition of reduced bone mass, with decreased cortical thickness and a decrease in the number and size of the trabeculae of cancellous bone (but normal chemical composition), resulting in increased fracture incidence. "Treatment with the FDA-approved ATP6V1A blocker etidronate, a bisphosphonate largely used in osteoporosis treatment, decreased levels of the amyotrophic lateral sclerosis associated protein ataxin-2 in cellular models and brains of adult Ataxin-2 mice." (PMID 39273013, 2024).
polyneuropathy (1 paper, 2025). A disease or disorder affecting more than one nerve. "INAS items related to polyneuropathy were more common in SCA3 MCs with an intermediate ATXN2 CAG repeat." (PMID 40684213, 2025).
retinitis pigmentosa (1 paper, 2020). Retinitis pigmentosa (RP) is an inherited retinal dystrophy leading to progressive loss of the photoreceptors and retinal pigment epithelium and resulting in blindness usually after several decades. "The present case presented gaze-evoked nystagmus without retinitis pigmentosa common in childhood SCA2 due to long CAG repeats in ATXN2 gene, greater than one hundred repeats." (PMID 32870233, 2020).
ZIKV infection (1 paper, 2019). "During ZIKV infection, we observed an increase in the abundance of Ataxin-2." (PMID 30944179, 2019). "However, changes in Ataxin-2 and G3BP1 levels might in part restrict the formation of SGs during ZIKV infection." (PMID 30944179, 2019). "Interestingly, independent of MOI, the levels of Ataxin-2 increased with ZIKV infection at 1 and 2 days postinfection." (PMID 30944179, 2019).
neurodegenerative disease (54 papers, 2009 to 2026). A disorder of the central nervous system characterized by gradual and progressive loss of neural tissue and neurologic function. "It is known that a number of neurodegenerative diseases, also called diseases of waiting, are associated with the expansion of the polyQ tract in the first exon of the ATXN2 gene." (PMID 39940702, 2025). "The yeast homolog of Ataxin-2, Pbp1, contains LSm and LSmAD domains similar to Atx2, an intrinsically disordered protein implicated in RNA biology and neurodegenerative disease." (PMID 40072111, 2025). "Meanwhile, intermediate-length repeat expansions in ATXN2 are more frequent in China, suggesting shared underlying etiological factors among neurodegenerative diseases." (PMID 35599735, 2022). "Here, we have generated and characterized a range of novel fly models of ataxin-2-associated neurodegenerative disease." (PMID 34077532, 2021). "Collectively, these studies provide a novel fly model for dissecting different pathogenic mechanisms of ataxin-2-associated neurodegenerative disease." (PMID 34077532, 2021). "Among minor genes, SH2B3 and ATXN2 were found to be associated with both autoimmune and neurodegenerative diseases." (PMID 33544228, 2021). "Structural variants within the genome can play a significant role in neurodegenerative disease risk, such as the repeat expansion in C9orf72 and the tri-nucleotide repeat in ATXN2, both of which are associated with familial and sporadic ALS." (PMID 32082115, 2020). "Overall, Ataxin-2 functions impact many metabolic processes and intersect with different disease-linked factors in human neurodegenerative diseases." (PMID 28587229, 2017). "polyQ expansion of ATXN2 has also recently been linked to the age-at-onset of a neurodegenerative disease closely related to ALS/SCA2, known as spinocerebellar ataxia type III (SCA3) or Machado-Joseph’s disease (MJD)." (PMID 28587229, 2017). "ATX-2 is the C. elegans ortholog of human Ataxin-2 that is implicated in human neurodegenerative disease." (PMID 27689799, 2016). "This scenario with ATXN2 loss-of-function affecting lipid homeostasis, while its excess causes neurodegenerative diseases, shows a striking similarity to the effects of TDP-43." (PMID 24659297, 2014). "In addition, RNA‐binding protein Ataxin‐2 (Atx2) is associated with the pathogenesis of various neurodegenerative diseases." (PMID 39392204, 2024). "It would therefore be important to determine whether N-terminal fragment accumulation is a factor in the progression of neurodegenerative diseases caused by ATXN2." (PMID 38128014, 2023). "We uncover a function for the conserved Pbp1/ATXN2 proteins in the promotion of retrotransposition, create and describe powerful yeast genetic models of ATXN2-linked neurodegenerative diseases, and connect the major aging mechanisms of rDNA instability and protein aggregation." (PMID 30417124, 2018). "Importantly, ATXN2 mutations are associated with neurodegenerative diseases." (PMID 30417124, 2018). "Thus, if R-loop accumulation emerges as a driver of pathogenicity in ATXN2-linked neurodegenerative diseases, magnesium supplementation and small molecule modulators of magnesium transporters and/or R-loop levels should be tested as potential therapeutic strategies within these clinical settings." (PMID 28587229, 2017). "We performed a genetic in-depth analysis of ataxin-2 (ATXN2), a gene that has already been described as a modulator of neurodegenerative diseases." (PMID 40684213, 2025). "It has been suggested a link between CAG repeat number in the HTT, ATXN1 and ATXN2 genes and different neurodegenerative diseases." (PMID 39974178, 2025). "Emerging research has highlighted the involvement of specific genes, including Sv2b, Park2, Sept5, Atxn2, Pink1, and Gabbr2, in neurological dysfunction and neurodegenerative diseases." (PMID 40943361, 2025).
neurodegenerative disease (continued). "ATXN2 is shown to modulate different neurodegenerative diseases like ALS or SCA3 by intermediate repeat length." (PMID 36894829, 2023). "First, assembly-promoting mutations in the Ataxin-2 gene or associated RNA binding and SG proteins such as TDP-43 can cause neurodegenerative disease." (PMID 33689682, 2021). "Work in a variety of model organisms including mice, now suggests that ATXN2 is a modifier of some neurodegenerative diseases." (PMID 31390360, 2019). "Using an HD animal model in which a mutant Huntingtin (mHtt) protein is expressed, we identify a role for the RNA binding protein and neurodegenerative disease gene Ataxin-2 (Atx2) in mediating mHtt effects on circadian behavioral rhythms." (PMID 31593562, 2019). "Several neurodegenerative diseases are associated with defects in key RNA-binding proteins including TDP-43, ATXN2, and FUS." (PMID 25806046, 2015). "In addition to Neprilysin-2 and FoxP, ataxin-2-, neuropeptide Y receptor-, and neurofilament heavy polypeptide-like proteins function in various neurodegenerative diseases." (PMID 40429204, 2025). "This supports the hypothesis that therapies that target ATXN2 may be effective for a wide range of neurodegenerative diseases." (PMID 31390360, 2019). "We also present the complete list of human proteins with PrLDs and discuss the prevalence of the PrLD in nucleic-acid binding proteins that are often connected to neurodegenerative disease, including: ataxin 1, ataxin 2, FUS, TDP-43, TAF15, EWSR1, hnRNPA1, and hnRNPA2." (PMID 26996412, 2016). "However, a loss-of-function of ataxin-2, in addition to its GOF, cannot be excluded, since both mechanisms seem to be important modulators of disease manifestation in several neurodegenerative diseases." (PMID 22916186, 2012). "A homozygous deletion of ataxin 2 (ATXN2), codifying for a RBP, was observed; it has been reported that silencing of ATXN2 gene, which is known to affect neurodegenerative diseases, led to disturbance in RNA transcription." (PMID 30486883, 2018). "Although it has been suggested that Ataxin-2 is a genetic modifier of numerous neurodegenerative diseases, further research is needed to clarify the role of Ataxin-2 in PD and MJD, as well as other neurodegenerative diseases." (PMID 28587229, 2017). "It is also unclear if the R-loop suppressing functions of ATXN2 and SETX may intersect in ALS and other neurodegenerative diseases." (PMID 25806046, 2015). "A recent survey of modifier genes in Saccharomyces cerevisiae, Caenorhabditis elegans and Drosophila melanogaster concluded that ataxin-2 orthologues are generic modifiers that affect multiple if not all neurodegenerative diseases." (PMID 25721894, 2015). "Considerable progress has been made deciphering the mechanism involved in aggregate formation of polyQ-expanded ATXN2 protein in neurodegenerative disease, but the function of non-CAG repeat expanded ATXN2 remains elusive." (PMID 32024018, 2020).
neurological diseases (20 papers, 2009 to 2025). "ATXN2 has been known as one of the few genes in which a single gene causes multiple diseases and/or alters different neurological disorders." (PMID 41462986, 2025). "ATXN2 is associated with multiple neurological diseases, and the variant is one of the top independent signal in our study." (PMID 33671795, 2021). "PolyQ expansions in ATXN2 are now associated with three clinically distinct neurological diseases; these different situations are associated with different repeat lengths and sequence configuration of the DNA repeat region." (PMID 21479228, 2011). "In particular, we found that dGOLPH3 interacts with the Drosophila orthologs of Fragile X mental retardation protein and Ataxin-2, suggesting a potential role in the pathophysiology of disorders of the nervous system." (PMID 34571985, 2021). "In conclusion, our results facilitate a better comprehension of the role of Ataxin-2 protein in humans, which can lead to potential treatments for ATXN2-related neurological disorders." (PMID 33984024, 2021). "In conclusion, our behavioral studies lay the groundwork for studying Atxn2 function in a number of neurological diseases." (PMID 19617910, 2009). "The ATXN2 gene (NCBI gene ID: 6311) encodes ataxin-2 (ATXN2) (Uniprot: Q99700), a large protein with low sequence complexity that shares no structural or functional similarities, apart from the polyQ tract, with other glutamine-rich proteins associated with neurological diseases." (PMID 38877004, 2024). "Interestingly, in one control nervous system from an individual who carried an ATXN2 intermediate length repeat expansion but did not have neurological disease, we observed rare nuclear depletion of ELAVL3 and dot-like inclusions in a few neurons in the motor cortex but not spinal cord." (PMID 34618203, 2021).
cancer (9 papers, 2015 to 2025). A tumor composed of atypical neoplastic, often pleomorphic cells that invade other tissues. "Continuing research efforts have unveiled ATXN2's interaction with various factors associated with tumorigenesis, providing novel avenues to explore the molecular mechanisms underlying cancer." (PMID 39039334, 2024). "Since evidence on the association of ATXN2 and multiple cancers is relatively sparse, our study provides supportive evidence from an epigenetic perspective of methylation, which requires deeper research in the future targeting related pathways." (PMID 37449541, 2023). "Using a combined CRC and EC GWAS meta-analysis, we have identified a region on chromosome 12q24.1 spanning two genes, SH2B3 and ATXN2, which contains a SNP that is formally associated at GWAS thresholds of significance with cancer risk." (PMID 26621817, 2015). "In other cancers, such as ovarian cancer, ATXN2 is linked to specific methylation profiles." (PMID 39039334, 2024). "Moreover, cg07932199 (ATXN2) was remarkably indicated to have potentially same driving variants as those contributing to susceptibility to cancers at breast, colorectum, endometrium and lung, in agreement with previous findings." (PMID 37449541, 2023). "In this study, we investigated the effect of HTT, ATXN1 and ATXN2 CAG allele sizes in the risk of developing the disease and cancer comorbidity in a large cohort of patients with iPD." (PMID 39974178, 2025). "This review has primarily focused on elucidating the exact roles of ATXN2 in cancer and its involvement in related cellular processes and signaling pathways." (PMID 39039334, 2024). "Aberrant DNA methylation at several CpG sites related to smoking, including cg06639488 (EFNA1), cg12101586 (CYP1A1), cg14142171 (HLA‐L) and cg07932199 (ATXN2), were indicated with cross‐cancer carcinogenic effects." (PMID 37449541, 2023). "mQTLs of CpG sites cg06639488 (EFNA1), cg12101586 (CYP1A1) and cg14142171 (HLA‐L) was validated by eQTLs at specific cancer tissues, and cg07932199 (ATXN2) provided colocalization evidence of both methylation and susceptibility to multiple cancers." (PMID 37449541, 2023). "Additionally, inhibiting ATXN2 through siRNA increases the efficiency of nanoparticle delivery to tumor cells, making ATXN2 a potential reference for nanoparticle delivery prediction in cancer cells." (PMID 39039334, 2024).